CD4 (CD4 molecule)
Diseases named in the same sentence as CD4 in open-access papers (continued):
Sharing a sentence is not in itself a finding about the gene and the disease.
tumor (continued). "Examining the correlation between the expression of the different factors (CD3+ T, CD4+ T, CD8+ T, lymphocytes, and CD19+ B) and tumor markers CA724, CA199, and CEA, it was found that CD4+T cells were negatively associated with CEA expression (P = 0.03)." (PMID 38259671, 2024). "This feature of CD8 coreceptor independence has important translational significance, since CD4+ TCR-T cells demonstrate direct recognition and killing of HLA-Ipositive/HLA-IInegative tumor cells, albeit at a slower rate compared with CD8+ TCR-T cells." (PMID 39287991, 2024). "Regulatory T cells (Tregs), CD4+IL2RA+FOXP3+, were found mixed with CD4 T cells from tumor samples (tCD4)." (PMID 39516494, 2024). "VISTA is predominantly expressed on TME-infiltrating myeloid cells (i.e., MDSCs and CD68+ TAMs), CD4+ and CD8+ T cells, and tumor cells." (PMID 38357542, 2024). "NKDCs/α-mPD-L1 combination increased migration of dendritic cells, CD4, CD8 T cells, and activated CD8 T cells to the tumor-bedding site, and promoted endogenous tumor-specific cytotoxic T-cell response." (PMID 38279092, 2024). "Our previous study showed that the combination of DSF/Cu and DTX increased the infiltration of CD8+ T cells and macrophages in tumor tissue, decreased the infiltration of MDSCs, and increased the activation of CD8+ and CD4+ T lymphocytes in the spleen of mice." (PMID 38370371, 2024). "Each segment was monitored for CD4+ and CD8+ T-cells and the counts expressed relative to the position of the tumor margin." (PMID 38204925, 2024). "Dysfunction of APCs hinders the activation and infiltration of CD4+/CD8+ T cells, IFN-γ producing cytotoxic T lymphocytes, and macrophages, thereby suppressing tumor immunity." (PMID 39845976, 2024). "While GOT2 is not essential for in vivo proliferation of cancer cells, its interaction with PPARδ constrains the spatial distribution of CD4 + and CD8 + T cells within the tumor microenvironment." (PMID 38459595, 2024). "Studies have shown that IL-17 reduces the presence of CD4 + and CD8 + lymphocytes in the tumor microenvironment, increases infiltrative Tregs, and further promotes angiogenesis, invasion, and metastasis." (PMID 38349411, 2024). "We noticed that most CD4+ and CD8+ T cells were distributed in the peripheral SB28 tumor area with only a few T cells found in the center area, which is different from the GL261 model." (PMID 38298111, 2024). "Vaccination with chimeric mTrop2 VLPs can break self-tolerance and initiate robust cellular and humoral immune responses, markedly enhancing the presence of CD4+ and CD8+ T cells, along with NK and natural killer T (NKT) cells, within tumor tissues." (PMID 38948057, 2024). "TILs participating in anti-tumor immunity in GBM IDH-wt include CD4+ and CD8+ and are key players in the host immune response to tumor." (PMID 39594814, 2024). "Macrophages can promote T-cell-mediated antitumor responses by presenting tumor antigens on major histocompatibility complex (MHC) class I and class II to CD8+ and CD4+ T cells, respectively." (PMID 39702278, 2024). "Multiomic analyses showed that CD8-low responders had an inflammatory tumor microenvironment pretreatment, enhanced by an influx of CD8 T cells, CD4 T cells, B cells, and macrophages upon treatment." (PMID 39190534, 2024). "They found that artemisinin boosted T cell functioning, blocked the immunosuppressive effects of Tregs and MDSCs, and allowed CD4+ IFN-γ+ T cells and cytotoxic T cells to thrive, all of which hindered tumor growth in vivo." (PMID 39050852, 2024). "Immune microenvironment analysis showed that, compared to CNRT, RTRT more effectively preserved lymphocytes within the tumor, particularly CD4+ T and CD8+ T cells, and maintained the tumor immune microenvironment." (PMID 39736508, 2024). "B cells function as antigen-presenting cells, activating CD4+ T and CD8+ T cells to directly target tumor cells." (PMID 39493764, 2024).
tumor (continued). "Animal studies have demonstrated that the global depletion of Tregs enhances anti-tumor immunity and facilitates tumor rejection, with effective tumor immunity being induced in vivo through the depletion of CD25+CD4+ T cells." (PMID 39457014, 2024). "We estimated and compared the CD4 + and CD8 + T cell abundance as well as tumor-infiltrating lymphocytes (TILs) scores in high and low cell density areas of the 21 heterogenous PF-EPN-A with available DNA methylation data." (PMID 38265527, 2024). "In general, macrophage showed highest infiltration, followed by CD4 T cells and CD8 T cells, all with higher infiltration in stromal than tumor regions." (PMID 39184073, 2024). "CD4+ and CD8+ TILs are key players in cell-mediated adaptive immunity and prevent tumor progression and metastasis." (PMID 38779258, 2024). "CD4+ and CD8+ T-lymphocyte tumor infiltrates, which are the most powerful effectors in anticancer immune response and constitute the backbone of cancer immunotherapy, were investigated." (PMID 39769460, 2024). "In A20 and Eμ-Myc tumours, we were able to detect dendritic cells, B cells, endothelial cells, CD4 + T cells, CD8 + T cells, macrophages, regulatory T cells (Tregs), tumour cells, neutrophils, and fibroblasts." (PMID 38311785, 2024). "We previously reported that a functional immune system is required for HDAC6 inhibition-mediated tumor suppression using immunodeficient SCID mice and CD4/CD8 T-cell depletion assays." (PMID 39272209, 2024). "The majority of CD4(+) T cells expressed either TNF-α and/or IFN-γ, indicating a T-helper 1 (Th1) subset predominance in the tumor infiltrates." (PMID 38895115, 2024). "The optimal CD4/CD8 ratio of chimeric antigen receptor (CAR) T cells is approximately 1:1, which confers a favorable advantage for eliciting an effective anti-tumor response within the host organism." (PMID 38637885, 2024). "This activation is crucial for enhanced antigen presentation to CD4+ and CD8+ T cells intratumorally, as well as in lymph node and spleen tissues and for differentiation into active tumor antigen-specific Ab-secreting B cells." (PMID 39791721, 2024). "Recruit lymphocytes and antigen-stimulated DCs, leading to increased infiltrates of CD4, CD8, and CD11c+DEC205+ dendritic cells in the tumor, creating a lymphoid-like microenvironment and facilitating cognate T cell activation." (PMID 38655260, 2024). "Conversely, IL-33 signaling encourages the proliferation of suppressive CD4+ Foxp3+ GATA3+ Treg cells, especially in tumor-specific environments high in IL-33." (PMID 40236667, 2024). "We prioritized identifying non-overlapping subsets of naive, memory, and regulatory both CD3+CD4+ and CD3+CD8+ subsets of T cells due to the different roles these cell types play in the tumor immune microenvironment." (PMID 39763680, 2024). "In the context of serial co-cultures with OVCAR-3 or MCF7 tumour cells, FOXO1 overexpression led to a significant increase in the recovery of CD8+ and CD4+ CAR T cells and similar levels of IFNγ and TNF production compared with control CAR T cells." (PMID 38600376, 2024). "To assess the cytotoxic potential of CD4+ and CD8+ pancreatic TILs, we measured the expression of the cytolytic molecules granzyme B and perforin in T cells isolated from both tumor and patient PBMCs." (PMID 38335302, 2024). "The results indicated that patients with enhanced PLIN3+ tumor cells had relatively low ratio and numbers of CD3+ T cells and CD3+CD4+ helper/inducer T cells in blood, whereas significance was lost within immunocytes and fibroblasts." (PMID 38554152, 2024). "Flow cytometry analysis revealed that greater numbers of CD4+ and CD8+ T cells per tumor mass had infiltrated the tumor compared to control treatments." (PMID 38803496, 2024).
tumor (continued). "In vivo, the transplantation of mPEI/M1mt excellently potentiates therapeutic effects of anti‐PD‐L1 by resetting an antitumor proinflammatory tumor microenvironment and stimulating CD8 and CD4 T cells dependent immune response." (PMID 39119940, 2024). "This patient who did not demonstrate a synergistic response was also an outlier in that their tumor contained the most CD45+ cells, increased proportions of DCs and MAIT cells, and decreased proportions of neutrophils and CD4+ Tregs." (PMID 38429349, 2024). "For analysis of tumor-specific methylation, we used control sample consisting of methylation data obtained from five normal human T cells - CD3, CD4_1, CD4_2, CD4_3 and CD8 - averaged out by Metilene." (PMID 38464090, 2024). "In MC38 tumors, the depletion of CD4+ T cells, CD25+ (T regs), or macrophages reduced tumor growth and supported PD-1 therapy." (PMID 38254785, 2024). "CD4+ T cells and CD8+ T cells displayed an enhanced expression of CD44 in TdLNs and Spl in WT mice during tumor progression." (PMID 39206204, 2024). "In general, ICIs promote the entry of CD4, CD8, and other tumor‐infiltrating lymphocytes (TILs) into tumors, where they subsequently kill tumor cells." (PMID 38013668, 2024). "A correlation of neutrophils with CD4+ T helper cells, CD45RO+ memory T cells, and CD20+ B cells was observed in the stromal compartment of central tumor samples." (PMID 39335132, 2024). "Since no cytotoxic CD8+ T cells were identified in the scRNA-seq data set for KPC tumor, we used naive CD4+ and CD8+ T cells as the point of origin for our analysis for that sample and found that these cells evolved into CD4+ and CD8+ Tregs within the tumor." (PMID 38888968, 2024). "A predominance of CD4 + T cells along with higher proportion of CD4 + Tem and CD8 + Tem were consistently identified when classified into sample types (tumor and LNs)." (PMID 38630265, 2024). "T cells, mainly consisted of CD4+ T helper cells and effector CD8+ T cells, are the major tumor-infiltrating lymphocytes in the TME." (PMID 39019859, 2024). "The ratio between different subgroups of T-cells thus provides an informative measure for tumor occurrence and progression, for example, the CD8+/CD4+ and CD8+/FOXP3+ ratios are the most-used measurement for the potency of anti-tumor immune activity." (PMID 38474377, 2024). "Using FACS analysis, we observed that mice inoculated with CD74‐Over KLN205 cells exhibited a decrease in the relative proportions of CD4+ T cells, CD8+ T cells and GZMK+ Perforin+CD8+ T cells in the blood, spleen, tumour tissue and lymph nodes." (PMID 39113235, 2024). "TRB and LUR have been shown to activate CD4+ and CD8+ T-cells as well, promoting the adaptive anti-tumour immune response, inducing their infiltration in vivo and the proliferation of activated effector T-cells in vitro." (PMID 38257245, 2024). "In tumor tissues from mice implanted with LLC‐PRPS2‐shCCL2 cells, a notable increase in CD4+ and CD8+ T cell percentages, alongside a marked decrease in TAMs, M‐MDSC, and PMN‐MDSC, was observed." (PMID 38952044, 2024). "Locally, higher numbers of CD4+ and CD8+ infiltrated into the tumor, as analyzed via immunohistochemistry." (PMID 38803496, 2024). "The lack of GSDMD also had no significant impact on immune populations in the spleen of tumor-bearing mice or on the phenotype of CD4+ and CD8+ T cells in the tumor-draining lymph nodes." (PMID 39224600, 2024). "As a result, the suppressive effect of tumor cells on the immune system is weakened, leading to a gradual recovery of immune function and normal production of CD3 + T cells and CD4 + T cells." (PMID 38834662, 2024). "Goeppert observed a decreasing trend in the density of CD4+ and CD8+ T cells in the tumor immune microenvironment as bile duct cancer progressed." (PMID 39845973, 2024). "Our findings revealed that CD4+Tregs in TC as well as CD8+Tregs in IM and TC exhibited weaker interactions with surrounding tumor cells." (PMID 39093404, 2024).
tumor (continued). "Tumor‐infiltrating total and activated (CD44hiCD62Llo) CD8+ and CD4+ T cells were more abundant in si/SN38‐NP group than others, and both CD4+ and CD8+ T cells were evenly distributed in the tumor core and margin." (PMID 38953306, 2024). "Following antigen recognition, CD3 (T‐cell receptor) initiates a signaling cascade that activates both CD4+ and CD8+ T cells, which are referred to as tumor infiltrating lymphocytes (TILs) and are involved in eliminating tumor cells." (PMID 38600057, 2024). "cDC1 is critical for cross-presenting tumor antigens to activate cytotoxic CD8+ T cells and is also required for priming earlier CD4+ T cells in certain solid tumors." (PMID 38927916, 2024). "In contrast, Xiong et al64 observed a substantial infiltration of CD3+, CD4+, and CD8+ cells into Smad4 KO tumor tissues." (PMID 40458305, 2024). "In tumor tissue, CAF-derived supernatant provided fatty acids to CD4+ TILs, which increased the expression of SCD and oleic acid (OA) content." (PMID 39543650, 2024). "Based on fluorescent markers of CD3, CD4, CD8, and CD31, we generated a 3d rendering of CD4 T cells, CD8 T cells, and blood vessels in the tumor." (PMID 38168288, 2024). "Next, we sorted T cells from tumor samples of four patients with advanced PSCC using flow cytometry and investigated the repertoires of sorted CD4 + T cells and CD8 + T cells for each patient." (PMID 38280010, 2024). "The same tendencies were seen when the association between a number of PD-L1+ lymphocytes distributed in tumour islets and stroma and the IL17A+CD4+-immune phenotype was assessed." (PMID 39409156, 2024). "These indicated the cell cycle inhibitors promoted the infiltration of both innate immune cells, i.e., NK cells, and adaptive immune cells, i.e., CD4+ and CD8+ T cells, into the tumor core." (PMID 39388278, 2024). "To further characterize the IMEC subsets within the tumor, we evaluated the interaction between MHC‐II receptors expressed on TECs and MHC‐II ligands expressed on CD4+ T cells." (PMID 38874280, 2024). "Dendritic cells initiate anti-tumor immunity by capturing and presenting tumor antigens, which activate CD8+ and CD4+ T cells." (PMID 38895621, 2024). "The observed decrease in circulating CD4+ Treg cells in CCA and HCC patients, at T0, observed here, indicates a possible migration of this T cell population into the tumor microenvironment." (PMID 39408071, 2024). "The expression of CD11, CD16, CD4, IgA, IgE, IgG, IgM, NKG2D decreased, while the expression of CD8 and MHC-II remained stable as the tumor volume decreased by the third capture." (PMID 38515744, 2024). "Epithelial cells were categorized as normal epithelial (Normal-EP) and tumor cells using the CopyKAT algorithm, and T cells were classified as CD8, CD4, and Treg based on gene markers." (PMID 39638994, 2024). "In a mouse model, this vaccination effectively generated strong tumor-specific CD4+ and CD8+ T cell responses, which resulted in considerable tumor rejection (60–80% survival)." (PMID 39654897, 2024). "The overall fewer CD4+ Th cells (19,1% CD4+, 80,9% CD8+ of all CD3+ T cells) were generally located more distant to tumor cell clusters compared to the CD8+ Tc cells." (PMID 38566984, 2024). "Tumor-infiltrating lymphocytes (TILs) are important members of the immune surveillance system for tumors and are mainly divided into CD8+ T cells and CD4+ helper T cells." (PMID 38933335, 2024). "As we noticed decreased anti-tumor efficiency of CD8+T cells from passage 1 to 4, we next tested for the anti-tumor efficiency of CD4+T cells in our chronic HS diet model." (PMID 38891044, 2024). "The performance evaluation of various machine learning classifiers in predicting tumor-infiltrating T cell levels, including CD3, CD4, and CD8 subpopulations, reveals insights into the effectiveness of these models for clinical applications." (PMID 38549936, 2024).
tumor (continued). "Here we analyzed CD4+ and CD8+ T cells following multiple doses of anti-metabolite chemotherapies in two murine tumor models to identify ICB targets to combine with chemotherapy." (PMID 39343508, 2024). "While VSV-p14 significantly increased tumor infiltration of CD8 T cells, VSV-p15 increased tumor infiltration of CD8 T cells and CD4 T cells." (PMID 38750591, 2024). "In contrast, the high densities of CD3+, CD4+, CD8+ and CD20+ in the TILs of the tumor nest are favorable prognostic biomarkers for NSCLC." (PMID 38674427, 2024). "Th1-dominant CD4+ T cells generate IFN-γ to maintain the maturation of MDSCs and thus mediate CTT-induced long-term anti-tumor immunity." (PMID 38791188, 2024). "Although blocking PD1 or PDL1 by itself did not affect the killing capacity in vitro, we noted that PD1 expression on CD4+ and CD8+ TAII cells increased following tumor infiltration." (PMID 38184565, 2024). "We therefore depleted either CD4+ or CD8+ cells and assessed the metastatic potential of either MSS or MSI tumor cells following tail vein injection." (PMID 38177458, 2024). "Lymph nodes typically show a monomorphic infiltration of atypical cells, in which tumor cells express CD3 and CD2 and lack CD5 and CD4." (PMID 38892108, 2024). "A lower CD4+/CD8+ ratio minimizes the presence of Tregs, favoring an immune environment conducive to direct tumor cell killing." (PMID 39769460, 2024). "This cancer nanovaccine was subcutaneously injected on HER2+ breast tumor-bearing mice and generated CD4+ and CD8+ immune responses, IFN-γ secretion, and a significant decrease of tumor growth and increase of life expectancy." (PMID 37587290, 2024). "We treated tumor-bearing mice with anti-CD3, anti-CD4, or anti-CD8 antibodies and found that neutralization of CD3+, CD8+, or CD4+ T cells indeed attenuated the tumor growth inhibition induced by Prmt3-KO." (PMID 39256398, 2024). "For the FCS/aPDL1 treated group, the percentages of both CD4+ and CD8+ T cells showed an obvious increase in the tumor, indicating that aPDL1 was successfully delivered into the tumor to revert the T cell exhaustion." (PMID 38280876, 2024). "This was associated with increased expression of IFNγ and granzyme B by CD4+ and CD8+ T cells of tumor-bearing Ac-CD4Cre mice compared to wt littermates." (PMID 38919612, 2024). "T lymphocytes, which include CD4+ helper and CD8+ cytotoxic T cells, are known for their pivotal roles in anti-tumor responses." (PMID 39452154, 2024). "An expansion of CD4+ CD25+ T cell population is observed in both peripheral blood and tumor microenvironment of HCC patients." (PMID 38571964, 2024). "In fact, CD4 T cells can kill cancer cells, if they express MHC II, induce tumoricidal macrophages, destroy the tumor vasculature through cytokine release and help CD8 T cells in the effector phase." (PMID 38429759, 2024). "Regulatory T cells (Tregs), constituting 5–7% of CD4+ T cells, predominantly express FOXP3, repressing anti-tumor immunity and promoting tumor growth." (PMID 39614322, 2024). "CD4+CD25+FOXP3+ Tregs are associated with poor prognosis in patients with ESCC, suggesting that CD4+CD25+FOXP3+ Tregs are crucial for enhancing the invasive ability of TC and facilitating tumor escape." (PMID 39264227, 2024). "CD4 and 5-LOX (ALOX5) mRNA levels were significantly more expressed in tumour samples than in normal tissues in both GBM and LGG." (PMID 38816839, 2024). "The results demonstrate high levels of PD-1-expressing CD3+CD4+ and CD3+CD8+ T-cells in SCLC patients compared to healthy donors, which has been also reported for other tumor types." (PMID 38255251, 2024). "CD4+ T-cell and CD8+ T-cell tumor infiltration is one of the key characteristics of effective cancer immunotherapy." (PMID 38238581, 2024).